INS (insulin)
Diseases named in the same sentence as INS in open-access papers (continued):
Sharing a sentence is not in itself a finding about the gene and the disease.
type 2 diabetes (continued). "The proxy of insulin sensitivity eGDR predicts all-cause mortality in type 2 diabetes, independent of confounders including DKD." (PMID 33715620, 2021). "β-cell dysfunction in type 2 diabetes suggests decreased insulin synthesis and secretion." (PMID 33918379, 2021). "GO and KEGG enrichment were used to identify the function of miRNA between before and after transportation, and the pathways related to energy supply were enriched, such as the insulin signaling pathway, type II diabetes mellitus, and sphingolipid signaling pathway." (PMID 34679870, 2021). "However, type 2 diabetes (T2D) is based on the inability of pancreatic β-cells to sustain a compensatory secretory response, leading to insulin secretory dysfunction and the pathogenesis of T2D." (PMID 34360006, 2021). "Type 2 diabetes in the elderly is characterized by a milder hyperglycemia due to delayed responsiveness of pancreatic beta cells to release insulin versus high levels of insulin, insulin resistance and a more severe hyperglycemia in adults." (PMID 34324578, 2021). "The control group indicated that electroacupuncture could reduce the blood sugar of type 2 diabetic rats and relieve the skeletal muscle insulin resistance." (PMID 33824679, 2021). "Our findings suggest that altered glucose-insulin homeostasis could be a shared mechanism for psychosis and type 2 diabetes, which could be genetic and/or environmental in origin." (PMID 33439216, 2021). "Insulin pulses are a marker of β-cell health, and secretory parameters, such as pulse amplitude, time interval and frequency distribution, are impaired in obesity, aging and type 2 diabetes." (PMID 34206296, 2021). "This real‐world study aims to describe the proportion of patients with a symptomatic hypoglycaemic event and the proportion of individuals with type 2 diabetes, who newly or recently initiated with basal insulin, achieving individual o general HbA1c target in Argentina." (PMID 33532606, 2021). "Therefore, improvements in obesity result in the improvement of insulin sensitivity and the prevention of type 2 diabetes." (PMID 34947237, 2021). "Regarding AD, type 1 diabetes insulin deficiency seems to be the main factor for increased tau phosphorylation, while hyperglycemia-induced tau cleavage with insulin disturbances could be the factor that leads to tau pathology in type 2 diabetes." (PMID 34069618, 2021). "It has been proposed that oscillatory insulin release is important to normal glucose homeostasis, and disturbance of oscillations could be detrimental and play a major role in type 2 diabetes." (PMID 33767668, 2021). "Low Zn levels may interfere with the ability of the pancreatic islet cells to produce insulin, especially in individuals with type 2 diabetes." (PMID 35046823, 2021). "Adults with type 1 diabetes reported slightly more optimal medication intake and fewer perceived barriers (i.e. lower total score ASK-12) than adults with non-insulin-treated type 2 diabetes (mean score: 21.2 ± 5.6 vs. 22.0 ± 6.0 respectively, p=0.005, Cohen’s d=0.14)." (PMID 36994341, 2021). "PTP-1B serves as a therapeutic target for type 2 diabetes by improving insulin signaling." (PMID 33800074, 2021). "The only randomized, prospective trial evaluating effects of long-term insulin treatment on risk of MACE following ACS in patients with type 2 diabetes indicated no benefit and the possibility of harm." (PMID 34158057, 2021). "Type 2 diabetes can be considered a nutritional disorder characterized by the inability of the body to respond to insulin, which leads to many complications, including kidney failure, retinopathy, lower-limb amputation, an increased risk of cardiovascular disease, and stroke." (PMID 34829598, 2021). "Whether it affects insulin levels in this model or in a model of type II diabetes awaits further investigations." (PMID 34639032, 2021).
type 2 diabetes (continued). "Additionally, the association of vitamin E with vitamin A and zinc improved glycemic control and insulin secretion in type 2 diabetics." (PMID 33919211, 2021). "In some cases, patients with type 2 diabetes are also treated with insulin." (PMID 33776933, 2021). "Type 2 diabetes (T2D) is characterized by chronic hyperglycemia secondary to the decline of functional beta-cells and is usually accompanied by a reduced sensitivity to insulin." (PMID 34069914, 2021). "In this study, using the multi-omics data of type II diabetes from the Integrative Human Microbiome Project, from 10,783 features, we conducted a data analytic approach to elucidate the relationship between insulin resistance and multi-omics features, including microbiome data." (PMID 33671853, 2021). "Similarly, the efficacy of ginger was reported in type 2 diabetic patients as demonstrated by reduced serum insulin level and enhanced insulin sensitivity compared to placebo." (PMID 34054538, 2021). "We revisit the adaptations that were made for use in T1D, and Insulin-Requiring Type 2 Diabetes (T2D) as it helps to build a cohesive account of the work in our clinic aimed at studying the pathophysiology of insulin secretion and insulin action in the Islet Transplant Recipients." (PMID 34335462, 2021). "Circulating FGF19 and insulin concentrations are positively correlated in patients with type 2 diabetes, suggesting that FGF19 may participate in insulin-dependent glucose regulation." (PMID 35145481, 2021). "Of note, participants with relatively high baseline insulin levels showed higher efficacy of 1-kestose, suggesting that dietary 1-kestose might be further used for clinical application in patients with type 2 diabetes." (PMID 34578862, 2021). "Type 2 diabetes is a disease that includes multiple metabolic dysfunctions characterised by hyperglycaemia that is the result of various degrees of pancreatic β-cell failure and reduced insulin sensitivity." (PMID 33387681, 2021). "The inability of insulin to sufficiently inhibit lipolysis results in the excess efflux of free fatty acids, which may contribute to type 2 diabetes development in this population." (PMID 34299261, 2021). "Indeed, intravenous infusions of rHDL to patients with type 2 diabetes stimulated glucose uptake into skeletal muscle, reduced plasma glucose levels, and increased insulin secretion confirming preclinical findings." (PMID 34095317, 2021). "Here we present the cases of two African-American women with pre-existing type 2 diabetes who developed severe COVID-19 requiring mechanical ventilation and concurrent severe insulin resistance with total daily insulin dose requirements of greater than 5 unit/kg." (PMID 33992101, 2021). "Indeed, studies taking admixture into account have shown that type 2 diabetes, insulin secretion, body mass index, obesity, and adiposity are the main clinical phenotypes associated with metabolic disorders." (PMID 33841501, 2021). "Our group on the contrary, has consistently found increased brain glucose uptake (BGU) during conditions of euglycemic insulin clamp in obese/insulin resistant individuals, and also in individuals carrying a loss-of-function variant of the gene AKT2 that increases the risk for type 2 diabetes." (PMID 33806715, 2021). "Whereas type 1 diabetes and insulin omission are the most common causes of DKA in people, the majority of ketoacidotic cats likely have type 2 diabetes, and many have a concurrent disorder such as acute pancreatitis, hepatic lipidosis, chronic kidney disease, or urinary tract infection." (PMID 33945208, 2021). "A direct consequence of this event is the increased production of cytokines, including IL-6 and TNFα, which interferes with the normal transmission of the insulin signaling favoring the onset of type 2 diabetes and further propagating the state of chronic inflammation." (PMID 34769261, 2021).
type 2 diabetes (continued). "In conclusion, chronic resistance exercise in rats with type 2 diabetes reduced the expression levels of musclin in the skeletal muscle and concomitantly improved hyperglycemia and the insulin sensitivity index by activating Akt/GLUT‐4 regulated signaling in skeletal muscle." (PMID 33955191, 2021). "Accordingly, excess DPP4 derived from adipocytes and/or hepatocytes may act as a local mediator of inflammation and adipose/hepatic tissue insulin resistance, thereby forming a link between obesity and the pathogenesis of type 2 diabetes and metabolic disease." (PMID 33691757, 2021). "GREM1 is an insulin antagonist and serum levels are high in type 2 diabetes (T2D)." (PMID 33606810, 2021). "Furthermore, chronic resistance exercise decreased fasting blood glucose and reduced QUICKI, the insulin sensitivity index, in type 2 diabetes model rats." (PMID 33955191, 2021). "Furthermore, TNFα expression is increased in obesity, further inhibiting the vasodilator effects of insulin in skeletal muscle, reducing blood flow and glucose uptake, and leading to type-II diabetes." (PMID 33687595, 2021). "Indeed, such pulsatility of insulin secretion is often missing in human diabetics, where it has been proposed as an important etiologic factor in type II diabetes." (PMID 34440212, 2021). "In addition, decreased insulin secretion appears to be a major factor in the development of type 2 diabetes in Asian population." (PMID 34893662, 2021). "For these reasons, the pharmaceutical development of PTP1B inhibitors may serve as a novel type of insulin sensitizer in the management of type 2 diabetes and other cardiovascular syndrome or obesity." (PMID 35008779, 2021). "In addition to enhanced wound healing, deh-T3β improved kidney and liver functions, reduced liver steatosis, and improved heart recovery after ischemia and insulin sensitivity in adipose tissue in a mice model of type 2 diabetes." (PMID 34356303, 2021). "Alanine, one of non-EAAs, was associated with impaired insulin secretion and an increased risk of incident type 2 diabetes in a population-based large cohort." (PMID 34912870, 2021). "In addition to adherence to a healthy lifestyle, exogenous insulin therapy is a typical component of managing hyperglycemia in type 1 and type 2 diabetes." (PMID 34174848, 2021). "This might collaborate to β dysfunction because some researchers suggest that a period of exposure to high levels of glucose and fatty acids can result in significant impairment of insulin secretion in individuals with a family history of type 2 diabetes." (PMID 33905625, 2021). "Overall, it is still unknown what the best exercise prescription would be (i.e., modality, volume, and intensity of exercise) to improve insulin sensitivity in patients with obesity and type 2 diabetes." (PMID 33960110, 2021). "However, insulin resistance in target tissues and the shortage of insulin production from pancreatic β-cells are the principal attributes of type 2 diabetes." (PMID 33535455, 2021). "However, if beta cell function is impaired/depressed (compensatory increase in insulin secretion is incomplete) in IR individuals, impaired glucose tolerance (IGT) occurs, putting individuals at risk of developing type 2 diabetes (T2DM)." (PMID 33438144, 2021). "HFD has been shown to reduce insulin sensitivity and promote the development of type 2 diabetes." (PMID 33796546, 2021). "Among patients with type 2 diabetes, those treated with insulin were more likely to be screened." (PMID 33594476, 2021). "The study finds that nutritional supplements and using metformin, insulin, or sulfonylureas to manage blood sugar may be helpful to reduce the mortality in patients with pulmonary TB and type 2 diabetes comorbidity." (PMID 34513785, 2021).
type 2 diabetes (continued). "Although the imbalance of insulin signaling has been extensively studied in several models of obesity and type 2 diabetes, only a few studies have addressed its role in DOXO-induced cardiotoxicity, and the underlying molecular mechanisms are still poorly understood." (PMID 33547494, 2021). "Moreover, the ratio of esterified to free carnitine is elevated in patients with type 2 diabetes and carnitine administration has been shown to improve insulin-mediated glucose disposal and storage in both diabetics and non-diabetic individuals." (PMID 34099314, 2021). "FGF1 is a promising agent for the treatment of type 2 diabetes by improving insulin sensitivity." (PMID 34149434, 2021). "In type 2 diabetes patients there is a high initial resistance to start with insulin." (PMID 34134649, 2021). "Indeed, several of the type 2 diabetes treatments target β‐cells to induce insulin secretion such as sulfonylureas, dipeptidyl peptidase 4 inhibitors (DPP4i) as well as drugs that act as GLP‐1R and GPR40 agonists." (PMID 34319011, 2021). "In patients with type 2 diabetes, insulin use varied between 30% and 41% across W1 to W7." (PMID 33594476, 2021). "Type 2 diabetes is characterized by the presence of high blood glucose levels due to the body’s resistance to insulin, which means that although this hormone is present in the circulation, the cells cannot use it properly to introduce the sugar into their interior." (PMID 33810048, 2021). "Type 2 diabetes is characterized by a mild chronic inflammatory infiltrate due to higher visceral adipose tissue, diminished glucose regulation and homeostasis, and poor peripheral insulin sensitivity." (PMID 34604534, 2021). "Of patients with type 2 diabetes, 20.6% were treated with insulin." (PMID 34468753, 2021). "In contrast, the effect of insulin treatment on endothelial function may depend on the achieved level of metabolic control in patients with type 2 diabetes." (PMID 34439553, 2021). "Decreased insulin sensitivity and impaired insulin secretion, both of which are characterized by chronic hyperglycemia, are the major pathophysiological characteristics of type 2 diabetes." (PMID 34641407, 2021). "G. Don leaves stimulated insulin secretion and prevented complications due to type 2 diabetes." (PMID 33435282, 2021). "We also highlight the role of the β-cell in the development of type-2 diabetes and discuss how dysregulation of one or several steps in the insulin granule life cycle may contribute to disease development or progression." (PMID 33146746, 2021). "Conversely, in type 2 diabetes (T2D), the inability of failing β-cells to secrete may be due to the limited biosynthesis of new insulin." (PMID 34436456, 2021). "Therefore, it is of interest to show the effect of β-Caryophyllene on insulin resistance in skeletal muscle of high fat diet and fructose-induced type-2 diabetic rats." (PMID 35540699, 2021). "In summary, polyphenols are contained in many fruits and vegetables whose effects could contribute significantly to an improvement of glucose metabolism and insulin sensitivity, possibly leading to the prevention of type 2 diabetes." (PMID 33923263, 2021). "A 2017 meta-analysis of 17 published randomized controlled interventions including 560 participants showed that consumption of low AGE diets reduced insulin resistance regardless of participants’ diabetic status, and also diminished fasting insulin levels in patients with type 2 diabetes (T2DM)." (PMID 34444961, 2021). "However, previous studies suggest that imidazole propionate is a product of microbiota, which impairs insulin signaling in type 2 diabetes." (PMID 33572513, 2021). "In addition, evidence from a population-based study showed that individuals with post-pancreatitis diabetes mellitus are more likely to receive insulin therapy by 16.8% at five years after diabetes diagnosis when compared with individuals with Type 2 diabetes." (PMID 33805259, 2021).
type 2 diabetes (continued). "Additionally, reduced first-phase insulin secretion was found to be the earliest and most detrimental defect in β cells in humans with impaired glucose tolerance (prediabetes) and type 2 diabetes." (PMID 34882233, 2021). "Type 2 diabetes (T2D) is characterized by chronic hyperglycemia due to an insufficient insulin secretion to effectively lower plasma glucose concentrations in the context of insulin resistance of target tissues." (PMID 34069914, 2021). "However, xenoestrogens can also provoke an excessive insulin signaling, contributing to the development of type II diabetes." (PMID 34822574, 2021). "Furthermore, it would be of value to study the effect of imatinib on the later stages of the type 2 diabetes, using db/db mice for instance, especially to study the effect on metabolic insulin sensitivity." (PMID 34214082, 2021). "Moreover, a clinical study demonstrated that insulin-induced decreased vascular compliance under physiological conditions was diminished in patients with type 2 diabetes." (PMID 34283877, 2021). "Insufficient insulin secretion is a key component of both type 1 and type 2 diabetes." (PMID 33641671, 2021). "In addition, mRNAs targeted by the up- and downregulated exo-miRNAs were associated with such pathways as maturity onset diabetes of the young, type II diabetes mellitus, and insulin signaling pathway." (PMID 33714195, 2021). "Furthermore, it is antagonistic to insulin in human target cells, increased in serum in obesity and, most strongly, in Type 2 diabetes and also upregulated in human liver biopsies from individuals with NAFLD/NASH." (PMID 33606810, 2021). "Furthermore, future research should study type I and type II diabetes separately since there are differences in disease pathophysiology and in the disease populations (i.e., insulin use and BMI)." (PMID 33477729, 2021). "In addition, we categorized patients with type 2 diabetes into two groups according to insulin use and conducted a further comparison among these groups." (PMID 34283877, 2021). "We hypothesized that MR blockade would improve insulin sensitivity in individuals with type 2 diabetes." (PMID 34350730, 2021). "Insulin treatment is required in many patients with type 2 diabetes and ACS." (PMID 34158057, 2021). "Fasting CPR could therefore represent a useful indicator of GV instability, especially in patients with type 2 diabetes and impaired endogenous insulin secretion." (PMID 33907279, 2021). "However, current literature in support of this theory is limited to animal models and explored in relation to insulin excess generated in the metabolic intolerance state in type 2 diabetes." (PMID 33889602, 2021). "In conclusion, adults with type 1 diabetes show slightly more optimal medication intake and fewer perceived barriers than adults with non-insulin-treated type 2 diabetes and more optimal medication intake behavior than adults with both insulin-treated and non-insulin-treated type 2 diabetes." (PMID 36994341, 2021). "In addition, studies showed that LF significantly improved insulin sensitivity in type-2 diabetic patients." (PMID 35223937, 2021). "In type 2 diabetes, arterial hypertension (AH), BMI, and patient’s age are of greater importance, while the level of glycated hemoglobin (HbA1c), duration of the disease, level of education and insulin therapy are of lesser importance." (PMID 33669655, 2021). "For instance, there was a perception that insulin makes type 2 diabetes worse." (PMID 33496671, 2021). "In skeletal muscle, LKB1 and AMPK enhance glucose transport, lipid and fatty acid oxidation, and insulin sensitivity, and may, therefore, be treatment targets for type 2 diabetes and obesity." (PMID 34735498, 2021). "All patients in the study used insulin and 78 (82.1%) had type 2 diabetes." (PMID 33568148, 2021).